SHH (sonic hedgehog signaling molecule)
Diseases named in the same sentence as SHH in open-access papers (continued):
Sharing a sentence is not in itself a finding about the gene and the disease.
non-small cell lung carcinoma (8 papers, 2016 to 2025). A group of at least three distinct histological types of lung cancer, including non-small cell squamous cell carcinoma, adenocarcinoma, and large cell carcinoma. "Numerous malignancies, such as retinoblastoma, breast, colorectal, and non-small cell lung cancer, are frequently linked to the growth of SHH pathway components, especially GLI transcription factors." (PMID 36900220, 2023). "SHH pathway components are genetically altered in approximately 14% of non-small-cell lung cancer (NSCLC) cases, canonically activating the signaling." (PMID 37149646, 2023). "We confirmed that SBE specifically repressed SHH signaling pathway to interfere the SHH-mediated non-small cell lung carcinoma progression and metastasis via arresting cell cycle." (PMID 28507311, 2017). "Our results suggest the potential for SBE as a chemotherapeutic agent for repressing tumorigenesis and progression of NSCLC via targeting SHH signaling in human non-small cell lung cancer." (PMID 28507311, 2017). "Chronic stress-induced neurotransmitter also activates CSCs through multiple cAMP-mediated pathways (including ERK, AKT, CREB, SHH, and ALDH-1) in non-small cell lung cancer (NSCLC)." (PMID 36707854, 2023). "Interestingly, the SHH-induced transcription factor GLI1, which is known for its involvement in stem cell renewal in non-small cell lung cancer, localized to the nuclei of most KRT5+ cells in the distal IPF lung, arguing for activation of the SHH pathway in these cells." (PMID 27423691, 2016).
coloboma (7 papers, 2006 to 2024). An abnormality in which a part of a structure in one or both eyes is missing. "Loss-of-function mutations in SHH can occasionally be associated with isolated coloboma along the spectrum." (PMID 30073412, 2019). "In addition, a genetic signaling cascade for coloboma centered around PAX2 has been elucidated involving SHH and BMP4 signaling as upstream regulators." (PMID 24412933, 2014). "Human mutations in LRP2, a non-specific co-receptor of SHH also known as megalin, can lead to Donnai–Barrow syndrome, in which large ocular globes can be associated with high myopia and partial colobomas, in contrast to Lrp2-mutant mice presenting micro/anophthalmia." (PMID 30073412, 2019).
leukemia (7 papers, 2015 to 2023). A malignant (clonal) hematologic disorder, involving hematopoietic stem cells and characterized by the presence of primitive or atypical myeloid or lymphoid cells in the bone marrow and the blood. "SHH has been reported to be associated with adverse effects in leukaemia." (PMID 28978082, 2017). "As previously reported, CML cells show increased SHH signaling pathways players, making them ideal candidates for leukemia development." (PMID 36836615, 2023). "The constitutively activated SHh signaling pathway has been shown to be important for growth or progression of liver, lung, stomach, breast, leukemia, and esophageal cancers." (PMID 31117185, 2019). "In addition, SHH signaling has been found to play a role in the self-renewal of leukemia stem cells (LSCs) for CML and multiple myeloma." (PMID 34202904, 2021). "It was demonstrated that SHH and GLI1 are expressed in leukemic cell lines and primary leukemic blasts, and recent evidence suggests that inhibitors of the Hh pathway could be effective in reverting leukemia chemoresistance." (PMID 25861282, 2015).
liver fibrosis (7 papers, 2013 to 2024). "Specifically, the activated SHH pathway has been shown to trigger steatosis, liver fibrosis, dysplastic nodules, and induce hepatocarcinogenesis in this mouse model." (PMID 38730691, 2024). "Natural killer T (NKT) cells also produce Sonic Hedgehog (SHH), promote collagen secretion, and transform stationary HSCs into MYFs, resulting in hepatic fibrosis." (PMID 38074679, 2023). "further investigated up-regulated hepatic expression of SHH-induced hepatic fibrosis and hepatocarcinogenesis in a transgenic mouse model." (PMID 38074679, 2023). "As with fibroblasts, activation of the SHH pathway results in the transdifferentiation of hepatic stellate cells into myofibroblasts, a key mechanism in liver fibrosis." (PMID 24622053, 2014). "The SHH signaling is suggested to be mediated through its immediate target GLI2 in hepatic fibrosis since GLI1 expression was found rather sparse in HSCs." (PMID 24312641, 2013). "This activation of the SHH pathway can then lead to liver fibrosis." (PMID 38730691, 2024). "Chung demonstrated that the hepatic expression of SHH might prompt the activation of hepatic stellate cells and induce the upregulation of certain fibrogenesis genes, thereby contributing to liver fibrosis and the onset of hepatocarcinogenesis." (PMID 38730691, 2024). "Moreover, through the regulation of MMPs/TIMPs balance, SHH pathway mediates IGFBP-7 knockdown-induced attenuation of hepatic fibrosis." (PMID 34905501, 2021). "Interestingly, it was found that IGFBP-related protein 1 (IGFBPrP1) leads to HSC activation and ECM synthesis, and promotes the development of liver fibrosis via the SHH pathway activation." (PMID 34905501, 2021). "Animal models of liver fibrosis induced by various methods, such as genetic ablation of Mdr2 or Ikkβ deletion, bile duct ligation, and a methionine and choline–deficient (MCD) diet, all showed activation of SHH signaling in livers." (PMID 30700007, 2019). "Although Smo inhibitors suppress liver fibrosis, overexpressing SHH increases collagen expression." (PMID 30744607, 2019).
meningioma (7 papers, 2020 to 2024). A generally slow growing tumor attached to the dura mater. "Recent large-scale genome sequencing studies have revealed that approximately 5% of meningiomas contain activating mutations in the SHH pathway, particularly in the SUFU gene." (PMID 39568072, 2024). "SHH pathway aberrations are also evident in meningiomas, tumours arising from the meninges surrounding the brain and spine." (PMID 39568072, 2024). "Further gene expression profiling studies have identified key genes involved in SHH pathway activation in meningiomas." (PMID 39568072, 2024). "Regarding the SHH-activating meningiomas (n = 7), while one of the three complex rearrangements was found in a non-skull base meningioma, all simple SVs (n = 4) were found in skull base ones (P = 0.43)." (PMID 37805627, 2023). "Similar observations have been made in meningioma cells, which display primary cilia and can enrich activating forms of SMO within them but are unable to transduce downstream SHH pathway activation." (PMID 37830570, 2023). "However, a recent publication suggests that SMO mutations may not be associated with an activation of the SHH pathway in preclinical models of meningioma, potentially challenging the efficacy of vismodegib in these tumors." (PMID 36181606, 2023). "Patched 2 receptor gene (PTCH2), a tumor suppressor in the Sonic Hedgehog (SHH) signaling pathway, appeared to be the most significantly upregulated gene in this group, implying that decreased expression of PTCH2 due to chr1p loss may result in increased aggressiveness of NF2-2 meningiomas." (PMID 36937440, 2023). "Using RNA-Seq, we demonstrated that meningiomas acquiring SVs on 2q35 and 7q36.3 led to ectopic expression of the Hh ligands, IHH and SHH, respectively, and Hh pathway activation." (PMID 37805627, 2023).
skin tumors (7 papers, 2013 to 2024). "We therefore evaluated whether genes involved in the SHH pathway are associated with the development of BCCs exclusively, SCCs exclusively, and overall KC, in a 25-year prospective population-based study of skin cancer in Australian adults, using well-characterized phenotypes." (PMID 35505292, 2022). "Numerous studies have indicated a close correlation between the aberrant activation of the SHH signaling pathway and the occurrence of various types of tumors such as cancers of skin, brain, liver, gallbladder, pancreas, stomach, colon, breast, lung, prostate, and hematological malignancies." (PMID 37884351, 2024).
autism (6 papers, 2011 to 2018). Persistent deficits in social interaction and communication and interaction as well as a markedly restricted repertoire of activity and interest as well as repetitive patterns of behavior. "Recently, a relationship has been suggested between BDNF, sonic hedgehog (SHH), and oxidative stress in autism." (PMID 25769033, 2015). "The authors found, that serum SHH levels in children with mild and severe forms of autism were significantly higher than the SHH level in healthy children." (PMID 25501422, 2014). "Serum SHH levels were recently reported in in 44 children with autism and 40 healthy children of 3 to 9 years of age." (PMID 25501422, 2014). "The SHH gene, though not identified by autism linkage or association studies, is functionally related to the Patched gene (PTCHD1), which is a strong autism candidate gene." (PMID 21999758, 2011).
brain cancer (6 papers, 2009 to 2024). A primary or metastatic malignant neoplasm affecting the brain. "Moreover, it has been shown that SHH in tumor microenvironment is important for controlling epithelial–mesenchymal transition (EMT) in the pathogenesis, and progression of tumors, including prostate, bladder and brain cancers." (PMID 34439999, 2021). "Aberrant expression of SHH as well as non-canonical SHH signaling results in TME remodeling, which in turn induces GLI1 upregulation in breast, pancreatic, and brain cancers." (PMID 34831357, 2021). "For example, while pediatric brain cancers are largely driven by epigenetic dysregulation and micro-environmental influences exert a greater effect on adult brain cancers, common molecular drivers between the two include MYCN, NOTCH, PI3K/AKT/MAPK/mTOR, WNT/−catenin, and SHH." (PMID 34055785, 2021).
epilepsy (6 papers, 2017 to 2025). A brain disorder characterized by episodes of abnormally increased neuronal discharge resulting in transient episodes of sensory or motor neurological dysfunction, or psychic dysfunction. "Here, we identified SHH-related alterations in neural development that align with the Patient 1 phenotype of hydrocephaly, epilepsy and cerebral palsy." (PMID 41023835, 2025). "With ZNF as important modulators of SHH signaling pathways, we postulate the role of these genes in neurological development and epilepsy." (PMID 39852778, 2025). "It has been widely demonstrated that SHH is involved in epilepsy through an enhancement of extracellular glutamate levels which triggers neuronal excitation thus leading to epilepsy." (PMID 39852778, 2025). "In this context, it is possible that the HFS-dependent release of SHH might mediate certain specific actions initiated by conditions with a high neuronal activity, such as epilepsy and ischemia." (PMID 28262835, 2017). "The exploration of such proteins will explain why SHH release is strictly high neuronal activity-dependent, and might have implications to the understanding of excitatory toxicity-related disorders, such as ischemia and epilepsy." (PMID 28262835, 2017).
Hydrocephalus (6 papers, 2019 to 2024). Hydrocephalus is an active distension of the ventricular system of the brain resulting from inadequate passage of CSF from its point of production within the cerebral ventricles to its point of absorption into the systemic circulation. "More recently, deletion of Gpr161 cilia-localized G-protein coupled receptor in mouse neuroepithelial cells and RGCs at early mid-gestation-induced derepression of Sonic Hedgehog (SHH) signaling, leading to hydrocephalus at birth." (PMID 36859317, 2023). "Addition of location and hydrocephalus into the radiomics model resulted in improved AUCs of 0.8403 and 0.8317 for WNT and SHH, respectively." (PMID 39375809, 2024). "When combining the 11 imaging features with tumor location and hydrocephalus information, the AUCs of the RLH model were 0.8403 for WNT, 0.8317 for SHH, 0.6451 for Group 3, and 0.6111 for Group 4 in the testing cohort." (PMID 33117690, 2020). "Incorporating location and hydrocephalus into the radiomics model resulted in improved AUCs of 0.8403 and 0.8317 for WNT and SHH, respectively." (PMID 33117690, 2020). "In contrast, most SHH MBs are laterally located in the cerebral hemisphere; and therefore, hydrocephalus is not as common as Group 3 MB." (PMID 33816256, 2021).
Parkinson disease (6 papers, 2015 to 2025). A progressive degenerative disorder of the central nervous system characterized by loss of dopamine producing neurons in the substantia nigra and the presence of Lewy bodies in the substantia nigra and locus coeruleus. "Dysregulation of the SHH pathway in the brain contributes to aging-related neurodegenerative diseases such as Alzheimer’s disease, Parkinson’s disease, and amyotrophic lateral sclerosis." (PMID 34307464, 2021). "Therefore, the SHH signaling pathway can protect dopaminergic neurons, which provides an important clue for developing the effective therapeutic strategies against Parkinson’s disease." (PMID 34307464, 2021). "Understanding the molecular dynamics of such SHH mediated graft-host signaling may have significant implications towards developing therapeutic approaches for Parkinson’s disease or more broadly applied in strategies supporting brain protection and repair." (PMID 26340267, 2015). "This is the first research in which FSH priming during CEPs of the NS assay is combined with directed differentiation of NSPCs towards the DA pathway by using a defined medium containing SHH, FGF8, and BDNF, a procedure with possible eventual clinical implications for Parkinson’s disease therapy." (PMID 40722636, 2025). "For instance, activation of the SHH pathway may protect dopaminergic neurons and attenuate inflammatory response through regulating the PI3K/Akt pathway in Parkinson’s disease." (PMID 34307464, 2021).
pulmonary fibrosis (6 papers, 2013 to 2025). Chronic progressive interstitial lung disorder characterized by the replacement of the lung tissue by connective tissue, leading to progressive dyspnea, respiratory failure, or right heart failure. "Further study will focus on the relationship of CGRP and SHH pathway on the proliferation and differentiation of lung stem cells in pulmonary fibrosis." (PMID 35132349, 2022). "Sonic Hedgehog (SHH) ligand is upregulated in airway epithelial cells in lung fibrosis and Patched1 (Ptch1) expression is elevated in pulmonary interstitial cells." (PMID 30744607, 2019). "Using well-known databases to predict miRNA targets, we found that SHH, an important profibrotic regulator of pulmonary fibrosis, was a candidate miR-193a target." (PMID 30744607, 2019). "During PQ-induced pulmonary fibrosis, Smo, SHH, and Gli1 levels increased in lung tissues." (PMID 30744607, 2019). "For example, fibroblast growth factor-10 was markedly suppressed in the subjects with progressive idiopathic pulmonary fibrosis, and both TGF-β1 and SHH signaling were identified as critical mediators of this effect in MSCs." (PMID 31952198, 2020).
squamous cell carcinoma (6 papers, 2006 to 2023). A carcinoma arising from squamous epithelial cells. "Although podoplanin-positive TICs in squamous cell carcinomas may use these mechanisms to initiate and sustain tumour growth, they may also proliferate rapidly through the activation of the SHH signalling pathway." (PMID 20196862, 2010). "We observed increased FOXM1 and SHH RNA expression in NSCLC cells and CSC‐treated Beas‐2B cells, even though the protein expression of both were predominant in H1703 (squamous cell carcinoma) and HCC827 (adenocarcinoma) cell lines, respectively." (PMID 36621828, 2023).
thyroid cancer (6 papers, 2018 to 2024). "In summary, activating the SHH pathway through mutations in the RAS/BRAF/MEK pathway and the presence of paracrine factors in the interstitial space of thyroid cancer cells can enhance GLI1 expression and activity." (PMID 38313845, 2023). "Patched-1 (PTCH1) receptor, which activated by binding SHH, marginally expressed all thyroid cancer cell lines, especially more expressed in BHT101 and CAL62 cells." (PMID 35406554, 2022). "Previous research studies have shown that BRD4 can promote the phenotype of thyroid cancer cells through the SHH pathway." (PMID 34956562, 2021). "Furthermore, the interstitial space of thyroid cancer cells can generate a paracrine factor that synergistically affects the SHH pathway, predominantly affecting the invasive behaviour of thyroid cancer cells." (PMID 38313845, 2023). "The other interesting finding was that the FLAG signal was much higher in HHIP G516R transfected lysates compared to HHIP-WT transfected lysates, indicating interaction of the G516R mutant protein with SHH might increase the HHIP protein amount in thyroid cancer cells." (PMID 30241415, 2018).
ameloblastoma (5 papers, 2013 to 2024). The most common odontogenic tumor, arising from the epithelial component of the embryonic tooth and usually affecting the molar-ramus region of the mandible or maxilla. "Within the MAPK pathway, the BRAFV600E mutation is found in 57% of ameloblastomas, while within the SHH pathway, Smoothened (SMO) mutations have been identified in 24% of ameloblastomas." (PMID 36127985, 2022). "Several studies have revealed that SHH signaling-associated molecules are expressed in odontogenic tumors including ameloblastoma." (PMID 23835807, 2013). "Here, we examined the association of SHH signaling with the cell proliferation of ameloblastoma using AM-1 cells." (PMID 23835807, 2013). "We examined the expression of SHH signaling molecules and investigated the involvement of the SHH pathway in the proliferation of ameloblastoma, the most common benign tumor of the jaws." (PMID 23835807, 2013). "In ameloblastoma, immunoreactivity for SHH, PTCH, GLI1, GLI2 and GLI3 was seen in almost all tumor cells, but not in the stromal cells." (PMID 23835807, 2013). "Our results suggest that the SHH signaling pathway is constitutively active in ameloblastoma and plays an anti-apoptotic role in the proliferation of ameloblastoma cells through autocrine loop stimulation." (PMID 23835807, 2013). "In this study, we examined the expression of SHH, PTCH and GLI proteins and elucidated the functional roles of the SHH signaling pathway, in the proliferation of ameloblastoma." (PMID 23835807, 2013). "Taken together, it seems that SHH plays an anti-apoptotic role in the proliferation of ameloblastoma cells." (PMID 23835807, 2013). "Little is known about the significance and function of SHH signaling in ameloblastoma." (PMID 23835807, 2013). "This expression pattern of BCL-2 was similar to that of SHH in ameloblastoma." (PMID 23835807, 2013). "Our present results suggest that inhibition of SHH signaling might be a good target for a molecular treatment for ameloblastoma, although further studies are needed to understand the precise role of the SHH signaling pathway in tumor progression." (PMID 23835807, 2013). "Keratocystic odontogenic tumour, which is in the same odontogenic tumor group as ameloblastoma, and also has PTCH dysfunction implicated in its pathogenesis has been shown to respond significantly to cyclopamine in a dose-dependent manner by targeting the SHH pathway." (PMID 27386018, 2015). "In the present study, we examined the expression of SHH, PTCH, GLI1, GLI2, and GLI3 in ameloblastoma and investigated their functions using an ameloblastoma cell line." (PMID 23835807, 2013). "We detected expression of SHH, patched, GLI1, GLI2 and GLI3 in the ameloblastoma specimens and AM-1 cells." (PMID 23835807, 2013).